IL6ST (interleukin 6 cytokine family signal transducer)
Diseases named in the same sentence as IL6ST in open-access papers (continued):
Sharing a sentence is not in itself a finding about the gene and the disease.
tumor (57 papers, 2007 to 2026). "IL6ST expression showed a significant association with age (p = 0.05), tumor grade (p < 0.0001) as well as with ER, PR, HER2 and TNBC status (p < 0.0001, < 0.0001, 0.0033 and 0.0001, respectively)." (PMID 35387118, 2022). "IL6ST expression is associated with longer survival.IL6ST expression is lower in TNBC than ER+ tumours." (PMID 34210062, 2021). "The transcriptional coactivator YAP1 (Yes1 associated transcriptional regulator) and IL6ST (interleukin 6 cytokine family signal transducer)-JAK (Janus kinase) signaling axis have a prominent role in tumor formation and growth, promoting cancer cell survival, proliferation, migration and metastasis." (PMID 35435804, 2023). "In addition, genes that were upregulated in tumor-derived iCAFs were associated with the regulation of the inflammatory response, namely, IL6ST, NFKBIA, NT5E, SERPINF1, and NFKBIZ, suggesting that they play roles in communicating with immune cells." (PMID 34976204, 2022). "In Cluster 10 (DCIS/LCIS), upregulated genes such as CPB1, COX6C, TFF3, and IL6ST reflect early-stage tumor characteristics and immune regulation." (PMID 41182757, 2025). "Osmr was predominantly expressed in tumor cells, while Il6st and Il6ra were homogenously expressed in all cell types." (PMID 38236642, 2024). "IL6ST, interleukin 6 cytokine family signal transducer, is an important member of a signaling axis with a prominent role in tumor growth, promoting cell survival, proliferation, migration, survival, and metastasis." (PMID 39600942, 2024). "We further validated that the representative core genes in the IL-6/JAK/STAT3 pathway (Il6st (Gp130), Fas and Stat1) and the late response of estrogen (St6gal, Areg and Serpina3) were highly reduced in shMCT-1 tumor when compared to scramble tumor." (PMID 38505617, 2024). "We also observed diminished expression of Nfatc3 and Il6st, which function as tumor suppressor genes in the mammary gland." (PMID 38334641, 2024). "Impaired degradation of YAP1 and IL6ST by either the ubiquitin-proteasome system or autophagy was shown to favor the growth of different tumor types." (PMID 35435804, 2023). "Next, we looked into the average expression of SMG1, STAT3 and IL6ST only in tumor cells from each patient and we performed a correlation analysis for the expression or each factor with SMG1." (PMID 36443756, 2022). "Previous studies from our laboratory have identified four genes (ANP32E, DSC2, ANKRD30A and IL6ST/gp130) that are specific to TNBC and were associated with lymph node metastasis (LNmets), the earliest indicator of tumor progression via distal spread." (PMID 35387118, 2022). "Conversely, the IL6R and IL6ST expression was regulated by a large number of miRNAs with a similar trend in different tumor types, indicating that miRNAs epigenetically regulate mainly the IL6 receptor complex." (PMID 34576335, 2021). "Differential analysis of IL6, IL6R, and IL6ST revealed that these genes were significantly modulated in most of the selected TCGA tumor cohorts (n = 33) compared to normal tissues." (PMID 34576335, 2021). "This study also showed that IL6ST expression was negatively correlated with both lymph node status and tumour size." (PMID 34210062, 2021). "IL6ST expression has also been shown to be higher in luminal tumours, which are characterised by a better clinical prognosis than other BC subtypes." (PMID 34210062, 2021). "IL6ST expression is higher in luminal tumours (ER+/PR+) than in other BC subtypes.Positive trend towards longer survival in IL6ST+ luminal A tumours." (PMID 34210062, 2021). "Our bioinformatic analysis revealed that IL6, IL6R, and IL6ST genes were significantly modulated in most of the cancers showing a tumor-dependent pattern." (PMID 34576335, 2021). "IL6ST levels have also been shown to negatively correlate with tumour size and grade, as well as with nodal or lymphovascular invasion." (PMID 34210062, 2021).
tumor (continued). "High expression of PLXNC1 manipulated IL6ST expression at the DNA level and activated tumor-related pathways such as the IL-6/STAT3 pathway." (PMID 32117710, 2020). "RT-PCR analysis of primary ES tumors confirmed the expression pattern of cell lines with strong expression of IL6R and IL6ST in all tumor samples." (PMID 26215971, 2015). "After the progression, the molecular testing revealed CCDC6-RET fusion in a liver metastasis, two novel RET fusions (IL6ST-RET and SLC41A3-RET), and an ALK fusion with a mutation allele frequency of 0.19% in circulating tumor DNA (ctDNA), including the known EGFR 19del." (PMID 41907614, 2026). "We postulated that the IL-6 identified in our data might interact with IL6ST expressed in tumor cells, immune and stromal cells." (PMID 39762212, 2025). "Furthermore, expression analysis based on scRNA data revealed that IL-6 is predominantly expressed by fibroblasts, tumour cells, and macrophages, while IL-6R and IL6ST are mainly expressed in tumour cells, CAFs, and various immune cells." (PMID 39858048, 2025). "Notably, IL6ST plays crucial roles in maintaining immune homeostasis, inflammatory responses, and metabolic regulation within the tumor microenvironment." (PMID 40725477, 2025). "Additionally, the results of the Transwell and tube formation assays showed that the promoting effect of FXR overexpression on tumor migration, invasion, and angiogenic ability was almost completely abolished by IL-6ST knockdown in A549 cells." (PMID 38360812, 2024). "In fact, YAP1 and IL6ST signaling pathways have a role in promoting liver tumors, and the impaired degradation of the two proteins by either the proteasome or macroautophagy has already been shown to promote tumor growth." (PMID 35435804, 2023). "Numerous studies have reported that IL6ST plays a role in tumor progression and metastasis." (PMID 35303925, 2022). "Looking into the expression of SMG1, IL6ST (IL-6 signal transducer) and STAT3 in single tumor cells from those datasets, we observed that higher expression of SMG1 co-localized in the same cells that had higher levels of IL6ST, being such association very strong with the STAT3 factor as well." (PMID 36443756, 2022). "We had previously connected low CD8 expression by cytotoxic T cells to the induction of the membrane‐bound receptor for IL‐33, suppression of tumourigenicity 2 (ST2)L14, 15; we included this receptor and IL6ST (CD130) as two promising factors for the validation of CD8Low T cells in tumour sections." (PMID 36504430, 2022). "The predicted receptors in tumor cells included IL6ST and ERBB2." (PMID 35784460, 2022). "This suggests that other significantly altered transcripts such as RPS28, CYP4Z1, and IL6ST may represent novel biomarkers or candidate regulators of tumor progression." (PMID 35992327, 2022). "Since the onset of inflammation and carcinogenesis can be regulated by epigenetic events, we aimed to investigate the interplay among DNA methylation, miRNA expression, and gene expression of IL6, IL6R, including transmembrane isoform, and IL6ST in different tumor types." (PMID 34576335, 2021). "In this way, IL6ST might serve as a marker to identify those ER+ tumours that are more likely to respond to readily-available endocrine therapy." (PMID 34210062, 2021). "However, while activating mutations of IL6ST are found in 60% of IHCA cases, they are detectable only in a small fraction of HCC tumours." (PMID 34047814, 2021). "Notably, the PLXNC1 promoted GC cell proliferation and metastasis by enhancing tumor-related signaling pathways and transcriptional activation of IL6ST." (PMID 32117710, 2020).
tumor (continued). "IL-6 antibody treatment inhibits in vitro cell proliferation and in vivo tumor growth in both ER+ MCF7 cells and TNBC, MDA-MB-231 cells through a blockade of STAT3 activation and associated downregulation of STAT3 target genes including SOCS3, IL6ST and genes involved in angiogenesis." (PMID 35053592, 2022). "Importantly, the pathway of IL6ST was directly correlated with SMG1 expression in most tumor types in line with previous observations and indicating that IL-6 axis could be an inducer of SMG1." (PMID 36443756, 2022). "However, the slight reduction of IL6ST observed in many tumors may partially affect the direct action of IL-6 on tumor cells." (PMID 34576335, 2021). "Both IL6ST and YAP1 have been shown to promote tumorigenic features of tumor cells, such as proliferation and migration." (PMID 35435804, 2023). "CD8Low T cell showed enhanced ST2L and IL6ST (CD130) expression compared to CD8High T cells which expressed elevated KLRD1 (CD94) and granzyme B levels within the tumour microenvironment (TME)." (PMID 36504430, 2022). "The results outlined that more than 60% of the total mirDIP-predicted miRNAs were significantly correlated (Pearson’s correlation value ≥ 0.3 or ≤ −0.3; p ≤ 0.05) with the expression of each gene in at least one tumor type (IL6: 67%, IL6R: 70% and IL6ST: 64%)." (PMID 34576335, 2021). "In order to test the tumor responsiveness to IL6, the expression of IL6R isoforms and IL6ST were evaluated in all TCGA tumors." (PMID 34576335, 2021). "To investigate the selective effects of IL-1a and IL-27 on certain tumor cell lines, we quantified mRNA expression for the subunits of the IL-1a (IL1R1, IL1RAP) and IL-27 receptors (IL27RA, IL6ST)." (PMID 31730010, 2019). "IL10 and the gene encoding its receptor IL10R were expressed mainly by TAMs, LIF and LIFR by tumor cells, IL6 and the genes for IL6 receptor subunits IL6R and IL6ST by both cell types." (PMID 27215396, 2016). "Relative expression levels of the eight genes of interest (AZGP1, BIRC5, DHCR7, IL6ST, MGP, RBBP8, STC2, and UBE2C) were compared between paired whole tissue sections and tumor-enriched specimens." (PMID 25218890, 2014). "We observed that miR‐224‐5p could bind to and inhibit IL6ST expression and JAK2/STAT3 signaling pathway, and the inhibition of NSCLC tumor growth and JAK2/STAT3 pathway by miR‐224‐5p could be reversed by IL6ST overexpression." (PMID 39840666, 2025). "By binding to IL6ST mRNA, miR‐224‐5p reduces IL6ST expression, suppresses the activation of the JAK2/STAT3 signaling pathway, and ultimately inhibits NSCLC cell proliferation and tumor growth." (PMID 39840666, 2025). "Moreover, CellChat analysis unveiled ligand-receptor pairs mediating communication between tumor epithelial cells and disulfidptosis-related TME subgroups, such as TNFSF12-TNFRSF12A, TNF-TNFRSF1A, OSM-(OSMR+IL6ST), OSM-(LIFR+IL6ST), HBEGF-EGFR, and EREG-EGFR." (PMID 38292868, 2024). "Additionally, older patients with a tumor exhibited elevated FUT2, FUT3, and FUT8 coexpression with tumor-promoting IL6ST, IL22RA1, TGFB1, and TGFBR1 genes compared with young tumor." (PMID 38456503, 2024). "The increase in secretion of IL-6 protein in conditioned media from Kin1-NULL cells was confirmed by ELISA, while bulk tumor RNA analysis of Kin1-WT and Kin1-NULL tumors showed changes in IL-6-related genes, with an increase in Il6, Il6ra, and Il6st found in Kin1-NULL tumors." (PMID 36883731, 2023).
tumor (continued). "The latest study showed that impaired degradation of two proteins, the transcriptional co-activator YAP1 and IL6ST (interleukin six cytokine family signal transducer), by CMA promotes tumor growth, and it demonstrated that YAP1 and IL6ST are novel substrates for CMA." (PMID 37509689, 2023). "Survival analysis showed a trend towards longer survival in IL6ST-expressing luminal A tumours (p = 0.06) but not in other subtypes." (PMID 34210062, 2021). "Compared with young patients with a tumor, we found that the epithelial subset cE03 showed elevated FUT2 and FUT3 and coexpression with tumor-promoting TGFB1 and interleukin 6 cytokine family signal transducer (IL6ST) gene expression in older patients with a tumor." (PMID 38456503, 2024). "In support of the hypothesis that CMA acts as a tumor suppressor in the liver, LAMP2A expression was reduced in HCC biopsies compared to their matched adjacent normal tissues, and an anticorrelation with YAP1 and IL6ST could be observed." (PMID 35435804, 2023). "Given the potential role of IL6ST/STAT3 axis in SMG1 regulation and the important role it might play in tumor antigenicity we interrogated the RNA expression data from TCGA repository so as to identify immune pathways that could be associated with the expression of SMG1." (PMID 36443756, 2022). "Moreover, we found that FXR upregulates IL-6 and IL-6ST expression but not IL6Rɑ, thus suggesting that IL-6/IL-6ST may mediate FXR-modulated Jak2/STAT3 activation and tumor metastasis in NSCLC." (PMID 38360812, 2024).
cancer (50 papers, 2004 to 2025). A tumor composed of atypical neoplastic, often pleomorphic cells that invade other tissues. "Since TGFB1 and IL6ST are the two modules with the highest degree of molecular connectivity, we compared the cancer types with which each of these modules is associated." (PMID 38054018, 2023). "This molecular classifier was based on the assessment of the expression level of 8 cancer-related genes (3 linked to proliferation and 5 linked to ER signalling, including IL6ST) and 3 reference genes using reverse transcription quantitative polymerase chain reaction (RT-qPCR)." (PMID 34210062, 2021). "The role of several interleukins in inflammation has been highly significant in the study of various cancers especially IL6ST, which is upregulated through its development." (PMID 39201290, 2024). "In this study, we demonstrate that CMA controls the levels of YAP1 and IL6ST, expanding the range of cancer-relevant proteins whose turnover is controlled by CMA." (PMID 35435804, 2023). "The complex signaling mechanisms of IL6ST evidently play critical roles in immunology and a wide range of cancers." (PMID 37306188, 2023). "IL6ST transduces signals concerning many biological processes including the immune response, inflammation, and embryonic development, whereas, in cancer, activation and dysregulation of IL6ST is considered to play a role in the progression of the disease." (PMID 30586414, 2018). "Studies had shown that the Il6ST-related signaling axis mediated cancer progression, and targeting IL6ST might be a potential approach for cancer therapy." (PMID 40038566, 2025). "But IL1RAP (p = 4.234 × 10−11), CXCL3 (p = 0), CXCL5 (p = 0), and CXCL6 (p = 0) gene expression levels had higher expression in ER-negative than ER-positive ones; whereas IL6ST was the only gene whose expression was higher in ER-positive cancer patients (p = 0)." (PMID 39201290, 2024). "In summary, these results suggest that the TGFB1 and IL6ST modules may have broader effects in cell communications in multiple cancer types." (PMID 38054018, 2023). "Evidence has also shown that STAT3 enables cross-talk of the JAK/STAT pathway with the other gp130/IL6ST-dependent pathways, contributing to cancer-promoting effects of the MAPK/MEK/ERK and PI3K/AKT signalling pathways, such as chemo-resistance and epithelial-mesenchymal transition (EMT)." (PMID 34834425, 2021). "IL6ST, KLF4 and PGRMC2 have been linked to cancer pathogenesis, and downregulation of their mRNA expression by miR-142-3p may therefore be worth elucidating in future studies." (PMID 26657485, 2015). "Interestingly, some authors had previously suggested IL6ST might instead correlate with malignancy, given its higher expression in infiltrating cancers compared with in situ or benign lesions." (PMID 34210062, 2021). "IL6ST is a signal transducer through which cytokines, such as IL6, perform pleiotropic functions in many cancer-related processes including inflammatory pathways." (PMID 38987822, 2024). "The overall survival analysis was performed stratifying the cancer samples of each TCGA cohort based on the expression mean value of IL6, IL6R, and IL6ST by using UCSC Xena tool." (PMID 34576335, 2021). "Computational analysis was performed on the Cancer Genome Atlas (TCGA) datasets to explore the role of IL6, IL6R, IL6ST, and IL6R transmembrane isoform expression and their epigenetic regulation in different cancer types." (PMID 34576335, 2021). "In neuronal cells, the cancer-related gene SLIT2 was found to be upregulated, as were six other cancer-related genes (PDGFRA, DDR2, RSPO3, IL6ST, NTRK2, and HEY1) in cardiomyocytes and one cancer-related gene (HSD3B1) in hepatocyte-like cells." (PMID 32127560, 2020). "To evaluate cancer stem cell related phenotypes, we used qPCR to determine the expression of STAT3A, STAT3B and IL6ST." (PMID 31864341, 2019).
cancer (continued). "The other genes upregulated belonged mainly to the “cancer” and cell death functions (NFAT5, BMO2K, DLST, IL6ST, FAM76B, and MGA)." (PMID 22619672, 2012). "We did not observe any significant difference in STAT3 expression and less expression of IL6R and IL6ST in cancer samples compared to paired non-neoplastic samples." (PMID 38979413, 2024). "Silencing of the CMA receptor LAMP2A increased the levels of both proteins without changes in mRNA expression, and further analysis demonstrated that YAP1 and IL6ST were direct CMA substrates, revealing a novel mechanism that controls the expression of two cancer-relevant proteins." (PMID 35435804, 2023). "Therefore, we highlighted the IL6ST/JAK/STAT pathway in the effect of LEPROT in cancer, which was profoundly involved in the proliferation of cancer cells, immune regulation, and CAF activation and function." (PMID 34804118, 2021). "Interestingly, three of the 29 subtype-specific ceRNA hubs, namely EGFR, IL6ST and MET, are listed in the Cancer Gene Census of the COSMIC database." (PMID 28052038, 2017). "Studies have reported that both STAT3 and HIF1-α can transcriptionally upregulate the expression of WTAP in some cancer cells, but we found that LPS-induced upregulation of WTAP was not affected by SC144 treatment, which inhibited the activation of STAT3 signaling by binding to IL6ST." (PMID 39007267, 2024). "Furthermore, we also determined that higher CD300LG levels, but not PTPRO, IL6ST or CD48, were associated with better overall survival in cancer patients." (PMID 38386350, 2024). "Moreover, regardless of the regulation of LEPROT in cancer, it maintained a high correlation with the IL6ST/JAK1/2/STAT3 pathway." (PMID 34804118, 2021). "Although IL6ST has been shown to activate several signaling pathways including STAT3, Janus tyrosine kinase (JAK), mitogen-activated protein kinase (MAPK), and phosphatidylinositol 3-kinase (PI3K), among them, STAT3 has been hypothesized to be a key downstream molecule in cancer." (PMID 30586414, 2018).